LINC00301 (long independently transcribed non-coding RNA 301)
Synonyms: C11orf64; NCRNA00301; MGC39681
Gene: Long non-coding RNA gene on chromosome 11 (60,615,720 to 60,687,267, forward strand). Ensembl gene ENSG00000293513.
Subcellular location: Membrane
Diseases named in the same sentence as LINC00301 in open-access papers:
LINC00301 is named in the same sentence as 6 diseases in open-access papers, as found by Europe PMC text mining. Sharing a sentence is not in itself a finding about the gene and the disease. The quoted sentences say what the papers report.
lung carcinoma (2 papers, 2020 to 2021). "LINC00301 can facilitate lung cancer progression and triggers an immune-suppressing microenvironment through regulating the HIF1α." (PMID 34355042, 2021).
non-small cell lung carcinoma (2 papers, 2023). A group of at least three distinct histological types of lung cancer, including non-small cell squamous cell carcinoma, adenocarcinoma, and large cell carcinoma. "FOXC1 mediates LINC00301 to promote the tumor progression and generate an immunosuppressive microenvironment in non-small cell lung cancer." (PMID 38111678, 2023). "Similarly, LINC00301 induces an immunosuppressive tumor microenvironment by modulating the CD8+ T cell/Tregs ratio in non-small cell lung cancer (NSCLC)." (PMID 37346034, 2023).
lymph node metastasis (1 paper, 2020). "Furthermore, multivariate cox regression analysis showed that higher LINC00301 expression (n = 60), advanced stage, and positive lymph node metastasis are unbiased prognosticators of overall survival (OS) of NSCLC patients." (PMID 32878637, 2020).
tumor (3 papers, 2020 to 2023). "Tumor volume and weight in LINC00301 KD nude mice were significantly repressed (~ 40% reduction in tumor weight for A549 cells and ~ 37% decrease in tumor weight for SPC-A-1 cells) compared to those of sh-NC treated mice." (PMID 32878637, 2020). "By contrast, tumor volume and weight of LINC00301 OE nude mice were noticeably increased (~ 2.5-fold increase in tumor weight for A549 cells and ~2.8-fold increase in tumor weight for SPC-A-1 cells) compared to pLenti-CMV-NC treated mice." (PMID 32878637, 2020). "LINC00301 KD significantly repressed tumor growth in vivo, and LINC00301 OE markedly facilitated tumor growth in vivo, suggesting that LINC00301 strikingly accelerated the A549 and SPC-A-1 cells tumorigenicity in the nude mice." (PMID 32878637, 2020). "Our results showed that LINC00301 acts as a crucial player in the tumor progression of NSCLC." (PMID 32878637, 2020). "Moreover, LINC00301 has been recently reported to play a role in tumor progression." (PMID 35769265, 2022). "However, LINC00301 did not seem to influence myeloid-derived suppressor cells (MDSCs; both granulocytic and monocytic) and tumor-associated macrophages (TAMs)." (PMID 32878637, 2020). "And our data showed that the tumor volume in nude mice treated with LINC00301 OE was markedly increased than that of in CTL group, while LINC00301 OE plus EZH2 KD significantly repressed tumor growth derived in nude mice when compared with LINC00301 OE group." (PMID 32878637, 2020). "We also discovered that LINC00301 facilitates NSCLC cell proliferation and migration/invasion, represses cell cycle arrest and apoptosis, and accelerates tumor growth in vitro and in vivo." (PMID 32878637, 2020). "Hence, we concluded that LINC00301 facilitated lung tumor secreting TGF-β1 to drive Treg cell infiltration and then repressed CD8+ T cell amount in the tumor microenvironment (TME)." (PMID 32878637, 2020). "However, LINC00301 is not correlated to extra clinical features, including age (p = 0.5764), gender (p = 0.3479), differentiation (p = 0.8549), smoking history (p = 0.5361), and histological tumor type (p = 0.2105) in NSCLC." (PMID 32878637, 2020).
LINC00301 also shares sentences with these, for which no sentence is quoted: cancer (1 paper); gastric cancer (1).